ASPM (assembly factor for spindle microtubules)
Diseases named in the same sentence as ASPM in open-access papers (continued):
Sharing a sentence is not in itself a finding about the gene and the disease.
tumor (continued). "In multivariate Cox regression models, high cytoplasmic ASPM expression remained an independent predictor of shorter BCSS (p = 0.007) and DMFS (p = 0.022) when considering other prognostic covariates such as nodal stage, tumor grade, mitosis score, and Ki67 index." (PMID 39594769, 2024). "Moreover, comparing with that in adjacent nontumor tissues, ASPM mRNA levels in all of the nine matched HBV‐RHCC tumor samples were increased (P = 0.003), implicating its potential role in the recurrence of HBV‐HCC." (PMID 34428354, 2021). "In addition, a co-expression was found between ASPM and CDK4 in human tumor tissues." (PMID 32742488, 2020). "This may indicate that high levels of cytoplasmic ASPM are important for tumourigenesis but not for tumour progression." (PMID 24830737, 2014). "We investigated the expression of ASPM, CCNB2, CDCA5, KIAA0101, PRC1, and UBE2T in 12 LUAD tumor tissues and their adjacent non-malignant lung tissues." (PMID 33937050, 2021).
cancer (65 papers, 2010 to 2025). A tumor composed of atypical neoplastic, often pleomorphic cells that invade other tissues. "ASPM, an abnormal spindle like microcephaly associated protein, which is overexpressed in 27 cancers." (PMID 38172945, 2024). "Reduced MCPH1 mRNA expression and ASPM mRNA over-expression have been implicated in the development of human carcinomas." (PMID 24830737, 2014). "Network 1 genes failed to separate the good and bad outcome groups, even though certain cell proliferation genes are known to be associated with these cancers, such as ASPM in GBM and BRCA1 and BRCA2 in OV." (PMID 22956898, 2012). "Furthermore, we predicted the association between the expression level of ASPM and the infiltration levels of different immune cells in cancer between various and types." (PMID 35515103, 2022). "In our case the associations of ASPM expression levels especially in the serous and endometrioid subtypes may hint at distinct roles of ASPM in these cancer types." (PMID 24830737, 2014). "Although this review has focused on the functions of CAMSAPs, γ-TuRC, and ASPM in animal cells and cancer, it is important to recognize that the principles of microtubule minus-end regulation are well-documented in the plant kingdom." (PMID 41464116, 2025). "More specifically, ASPM-2 can influence the biological behavior of cancer cells by increasing their cell cycle stability and interacting with the Cdk2/cell cycle protein E (Cyclin E) complex." (PMID 40979592, 2025). "Currently, ASPM has been shown to play a role in a variety of cancers, including pancreatic, gastric, and cholangiocarcinomas." (PMID 40979592, 2025). "Given our positive results regarding the involvement of ASPM in RT‐resistant cancer cells, we forecast its effectiveness as suggested by homology modeling." (PMID 40873651, 2025). "NCAPG, NCAPH and ASPM have strong positive correlations with NCAPD2 expression in different cancers, especially in THYM." (PMID 38172945, 2024). "In these two types of cancers, higher expression of ASPM was evidenced in cancer tissues with respect to normal corresponding tissue, in late-stage cancers versus early-stage ones." (PMID 38903178, 2024). "Recently, the role of ASPM in conferring a malignant phenotype and regulating cancer stemness was extensively reviewed." (PMID 38903178, 2024). "Further clinical trials are warranted to explore the potential of ASPM as a target for therapeutic interventions in cancer." (PMID 39594769, 2024). "Since the involvement of ASPM in the Wnt signaling pathway has been reported in several cancers, the mediation of KIF11 throughout this mechanism should be explored in different cancers to give insights for targeted drug development." (PMID 38672404, 2024). "It has been demonstrated that ASPM plays a role in regulating Wnt signaling and cancer stemness in PDAC." (PMID 38791174, 2024). "In conclusion, recent research in different malignant tumors revealed that ASPM is highly expressed in a wide range of human malignancies and is linked to aggressive malignant features, worse outcomes, and recurrence." (PMID 39594769, 2024). "As an essential gene involved in regulating cell division, ASPM also contributes to cancer development." (PMID 37599996, 2023). "In conclusion, these results indicate that ASPM contributes to the cancer progression of RCC by targeting the Wnt3a signaling pathway." (PMID 37928425, 2023). "To verify the search results of the OncoLnc database, we searched the GEPIA database to predict the relationship between the transcription level of ASPM and cancer prognosis." (PMID 35515103, 2022). "ASPM expression was significantly higher in late-stage cancers than in early-stages cancers (e.g., KIRC, KIRP, LIHC, LUAD, and BRCA; p < 0.05), demonstrating a possible role of ASPM in cancer progression and invasion." (PMID 35515103, 2022).
cancer (continued). "ASPM is identified as a novel regulator of Wnt signaling, facilitating neurogenesis in the developing brain and contributing to the oncogenicity in cancer cells." (PMID 35387319, 2022). "Previous studies have shown that ASPM is highly expressed in a variety of cancers and is related to a poor clinical prognosis and recurrence." (PMID 35515103, 2022). "The mRNA levels of ASPM in various types of cancer tissues and their corresponding normal tissues were analyzed using the TIMER and DriverDB databases." (PMID 35515103, 2022). "Evidence indicated that ASPM, which is in the spindle poles, centrosomes, and midbodies, promotes cytokinesis and proliferative abilities of transformed human cell lines, human cancer cells, as well as fetal tissues." (PMID 36304312, 2022). "The study demonstrated that the expression of ASPM correlated with the prognosis of several human cancers, including KIRC and LIHC." (PMID 35515103, 2022). "Following the rescue of β-catenin in ATC cells, the reduction of Wnt signaling target genes and the impaired proliferation abilities of cancer cells induced by ASPM knockdown were obviously restored." (PMID 35387319, 2022). "In the present study, the intersection analysis of the KIFC1-interacted proteins and the KIFC1-correlated genes identified two genes, ASPM and TUBB, as the potential important regulatory molecules that are associated with KIFC1 for cancer cell division." (PMID 35327439, 2022). "Utilizing the UCSC Cancer Genomics Browser, hierarchical clustering of hub genes indicated that the expression levels of ASPM were higher in the HCC samples." (PMID 36304312, 2022). "Prior studies have also identified that ASPM-mediated activation of Wnt/β-catenin signaling contributes to the tumorigenicity of cancer cells, which is in line with our findings." (PMID 35387319, 2022). "Recently, aberrant expression of ASPM has been reported in various types of human cancers, and ASPM has been identified as a potential marker for many tumors." (PMID 34428354, 2021). "Here, we have shown that inhibiting ASPM expression sensitizes cancer cells to ionizing radiation and confers a synthetic lethality effect when combined with PARP inhibitor treatment." (PMID 34142045, 2021). "Several studies have reported that ASPM acts as an essential regulator of the Wnt signalling process, which enhances tumorigenicity in cancers and facilitates neurogenesis in brain development." (PMID 31905171, 2020). "Several of them were involved synthetically lethal genetic interactions, especially for RECQL4, TOP2A, MKI67 and ASPM, indicating their potential roles in drug design and cancer treatment." (PMID 32040444, 2020). "Activation of CCNB2 and ASPM genes induces tumorigenic phenotypes in a number of cancers, whereas their inhibition abrogates cellular proliferation in mice and induces genomic instability." (PMID 23282137, 2013). "Previous publications have indicated that ASPM levels are upregulated in various cancers at the RNA level." (PMID 21505456, 2011). "Future in‐depth analyses of why ASPM expression differs, how to specifically inhibit it, and the development of ASPM‐specific drugs will provide insights on how best to implement strategies for accurate diagnosis and selection patients for treatment of RT‐resistant cancer." (PMID 40873651, 2025). "At this time, we speculate that these regions participate in the inhibition of ASPM in RT‐resistant cancer cells." (PMID 40873651, 2025). "Although the importance of genomic stability in cancer development and progression is well established, the question of whether downregulating ASPM expression can increase apoptosis in RT‐resistant cells such as A549‐R remains unanswered." (PMID 40873651, 2025). "Emerging evidence suggests that ASPM is involved in the regulation of cancer cell stemness." (PMID 39594769, 2024). "Therefore, ASPM has the potential to be utilized as an additional marker for progression and transformation in these cancer types." (PMID 39594769, 2024).
cancer (continued). "Interestingly, ASPM was found in EV derived from serum, urine, and different types of cancer cells; FANCD2 in EV of serum, urine and CRC cells; and PIWIL4 (a canonical RBP) was also found in serum, urine and CRC cells." (PMID 38903178, 2024). "Gedevo alignments are also related to multiple cell cycle functions, and some of them show evidence of dysregulation in cancer (ASPM, CENPF, TOP2A, and TPX2) and the acquisition of two hallmarks of cancer: sustaining proliferative signaling and evading apoptosis." (PMID 36661515, 2023). "However, the potential correlation of ASPM expression with immune cell infiltration in other cancers remained unclear." (PMID 35515103, 2022). "The results revealed that ASPM expression was significantly upregulated in most cancer tissues." (PMID 35515103, 2022). "Researchers have found that ASPM acts as a novel regulator in promoting stemness by augmenting Wnt-Dvl-3-β-catenin signaling, and activation of Wnt signaling in cancer stem cells contributes to cancer progression in malignant tumors." (PMID 36304312, 2022). "ASPM is expressed in a variety of embryonic and adult tissues and is upregulated in cancer." (PMID 36012418, 2022). "In addition, the expression level of ASPM has an important impact on the biological behavior of cancer cells or the prognosis of patients." (PMID 33986994, 2021). "The tumorigenic roles of ASPM have been proposed in diverse cancer types." (PMID 34987580, 2021). "ASPM overexpression has been observed in various cancers and thus might serve as a prognostic marker in various contexts." (PMID 34142045, 2021). "Increasing evidences demonstrate the crucial role of ASPM in cancer progression." (PMID 34987580, 2021). "We hypothesized that circGPC3 competes with ASPM for binding to miR-378a-3p, leading to the modulation of cellular cancer phenotypes." (PMID 34199580, 2021). "In addition, ASPM is also known to regulate mitosis through controlling microtubule disassembly and is widely highly-expressed in a wide range of malignant tumors, including EOC." (PMID 33726773, 2021). "Based on this information, and combined with our new data, we posit that ASPM could be a promising therapeutic target in cancers characterized by ASPM-overexpression." (PMID 34142045, 2021). "We also observed somatic variants in several known cancer-associated genes (for example, JAG1, PRDM2, PRDM8, SETD2, ASPM, ZIC, GRIK1, etc.), which may be important for cell growth and proliferation." (PMID 30871634, 2019). "To address this issue, we assessed the expression of genes associated with metastatic ability and stem cell function such as KCNMA1 and ASPM, which has been reported earlier to serve as prognostic molecular markers of the metastatic process and cancer stem cell maintenance, respectively." (PMID 25796627, 2015). "Furthermore, many genes in cancer-related pathways were also over-expressed in high CIN samples including proliferation (ASPM, CKS1B, MCM gene family, TOP2A, TTK, TYMS) and cancer testis antigens (MAGE family)." (PMID 23840451, 2013). "Recently, both ASPM and microcephalin have been shown to be deregulated in a variety of cancers." (PMID 21505456, 2011). "Therefore, ASPM could be a target molecule for preventing RT resistance in a broad range of cancer types, prevention being a much better alternative than having to treat resistant cancer after it develops." (PMID 40873651, 2025). "Notably, ASPM expression significantly affected the prognosis of different cancers." (PMID 35515103, 2022). "ASPM might constitute a promising target for synthetic lethality-based cancer therapy." (PMID 34142045, 2021). "However, recent studies have shown that ASPM may promote cell proliferation and be involved in various human cancers." (PMID 34428354, 2021). "Therefore, we speculated that ASPM may act as a pan‐cancer driver gene and present a promising broad‐spectrum anticancer molecular target." (PMID 34428354, 2021).
cancer (continued). "Inhibition of ASPM expression promotes HERC2-mediated BRCA1 degradation, compromises HR repair efficiency and chromosome stability, and sensitizes cancer cells to ionizing radiation." (PMID 34142045, 2021). "The relationship between ASPM and CDK4 or CCND1 and the related mechanism should be further explored, and perhaps the role and the mechanism are different in different kinds of cancers." (PMID 32742488, 2020). "Strikingly, there is evidence thatANLN, ECT2, PRC1,RACGAP1, ASPM, and PLK1 areupregulated in a variety of human cancers and that their overexpression oftencorrelates with poor outcome (see for example and references therein)." (PMID 21386884, 2011). "For example, ASPM, ECT2, AURKA, BIRC5, CENPF, and EZH2 are amplified in several cancers." (PMID 36612203, 2022). "Previous studies showed that ASPM, ACTC1, and CCNB1 are related to cancer prognosis." (PMID 34434217, 2021). "Notably, we were able to experimentally demonstrate the circGPC3/miR-378a-3p/ASPM axis through luciferase assays, Ago2, RIP and circRNA pull-downs, as well as cancer phenotype assays." (PMID 34199580, 2021). "In this regard, the panCSC regulator ASPM, which we showed has a strong and robust prognostic role in PDAC, may provide the first pathway (Wnt)‐ and biology (cancer stemness)‐informed prognosticator in PDAC." (PMID 31465125, 2019). "However, it is unclear whether the interactions among KIFC1, ASPM, and TUBB have synergistic effects on the progression of cancer." (PMID 35327439, 2022). "Here, we summarize the neurological and non-neurological functions of ASPM and provide insight into its implications for the diagnosis and treatment of MCPH and cancer." (PMID 37599996, 2023). "Gene expression analysis showed that clonogenic side population cells in cancers express genes involved in the cell cycle and mitosis (e.g., SKA1, CCNB1, CDC25C, CDC2, BIRC5, CENPE, AURKB, KIFs, TOP2A, ASPM) more strongly than non-side population cells." (PMID 23962337, 2013).
nervous system disorder (2 papers, 2015 to 2021). A non-neoplastic or neoplastic disorder that affects the brain, spinal cord, or peripheral nerves. "In addition to homozygous causal variants in ASPM or CENPJ, we discovered additional heterozygous modifier variants in WDR62, CEP63, RAD50 and PCNT—genes already known to be associated with neurological disorders." (PMID 34068194, 2021).
neurodevelopmental disorder (2 papers, 2020 to 2022). A behavioral and cognitive disorder with onset during the developmental period that involves impaired or aberrant development of intellectual, motor, or social functions. "This opens the possibility that, as well as causing MCPH, mutant ASPM potentially contributes to other neurodevelopmental disorders such as ASD through altered parvalbuminergic interneuron development affecting cognitive behaviour." (PMID 32066665, 2020). "ASPM mutations may play a role also in other neurodevelopmental disorders, nevertheless, we lack the details of how or to what extent." (PMID 32066665, 2020).
infection (1 paper, 2023). The state of being infected such as from the introduction of a foreign agent such as serum, vaccine, antigenic substance or organism. "ASPM and TOP2A were significantly overexpressed at 24 h post-infection in SCs demonstrated by western-blotting." (PMID 37478057, 2023). "Four genes (ASPM, CENPF, MKI67, and TOP2A), which are well documented as stem cell and cell proliferation markers, were overexpressed at 24 h post-infection." (PMID 37478057, 2023).
neoplastic disorders (1 paper, 2022). "Abnormal spindle-like microcephaly associated protein homolog (ASPM) is a protein expressed in a variety of embryonic and adult tissues, including canine epididymal fluid, and is upregulated in cases of neoplastic disorders." (PMID 36548858, 2022).
ASPM also shares sentences with these, for which no sentence is quoted: autism (3 papers); gastric cancer (3); triple-negative breast carcinoma (3); anemia (2); Lissencephaly (2); liver cirrhosis (2); renal agenesis (2); Seckel syndrome (2); adenocarcinoma (1); autism spectrum disorder (1); Autosomal dominant microcephaly (1); bipolar disorder (1); Bloom syndrome (1); breast invasive carcinoma (1); Chagas disease (1); cholangiocarcinoma (1); clear cell renal cell carcinoma (1); developmental delay (1); endometrial adenocarcinoma (1); esophageal cancer (1); gallbladder cancer (1); hereditary spastic paraplegia (1); Infertility (1); kidney cancer (1); liver disease (1); Macrocephaly (1); nephropathic cystinosis (1); Nijmegen breakage syndrome-like disorder (1); ovarian endometriosis (1); papillary thyroid cancer (1).
A further 13 diseases each share a sentence with ASPM in 1 paper.